RUNX2 (RUNX family transcription factor 2)
Diseases named in the same sentence as RUNX2 in open-access papers (continued):
Sharing a sentence is not in itself a finding about the gene and the disease.
colorectal cancer (28 papers, 2012 to 2025). A primary or metastatic malignant neoplasm that affects the colon or rectum. "Recent studies have shown the association of RUNX1 and RUNX2 with TGF-beta signalling pathways in colorectal cancer, suggesting a potential association of GATA-1 with CRC through RUNX1SP1." (PMID 22852817, 2012). "In colorectal cancer, RUNX2 influences MAP kinase signaling via regulation of multiple RTKs, and its absence, can lead to resistance against MEK inhibitors along with its cofactor CBFB." (PMID 39876058, 2025). "RUNX2 is upregulated in gastric cancer, and in colorectal cancer patients, the expression levels of RUNX2 and MSN are significantly correlated, with both being overexpressed." (PMID 38430423, 2024). "In a colorectal cancer study that enrolled 75 cancer patients, cancer tissues displayed high RUNX2 levels compared with normal adjacent tissues." (PMID 37108164, 2023). "The results from an additional colorectal cancer study indicated the ability of RUNX2 to induce EMT and sphere formation in cancer." (PMID 37108164, 2023). "CBFβ was characterized by its biological function in promoting cell migration and invasion in colorectal cancer cells, and the modulation depended on RUNX2." (PMID 37108164, 2023). "Our findings suggest that MSN facilitates the progression of colorectal cancer by activating the β-catenin–RUNX2 axis, highlighting the potential of MSN as a promising therapeutic target for treating CRC." (PMID 37446127, 2023). "The invasion and migration capability of colorectal cancer cells were positively regulated by RUNX2 via a RUNX2-BRG1 complex and the CD44 signaling pathway." (PMID 37108164, 2023). "LncRNA-MALAT1 has been shown to promote colorectal cancer metastasis by interacting with RUNX2 at different steps of transcription and translation." (PMID 36429115, 2022). "Liquiritigenin exerted significant inhibitory effects on the invasiveness and epithelial-mesenchymal transition of colorectal cancer cells by downregulating runt-related transcription factor 2 (Runx2) and inactivating the PI3K/AKT signaling pathway." (PMID 35082907, 2022). "Wang and colleagues verified the promoting effect of Cbf-β in colorectal cancer progression in a RUNX2-dependent manner." (PMID 36483054, 2022). "For instance, Cbx4 represses the expression of Runx2 and metastasis of colorectal carcinoma, which is dependent on its interaction with HDAC3." (PMID 30357595, 2019). "MSN promotes colorectal cancer progression through the β-catenin-RUNX2 signaling axis." (PMID 38430423, 2024). "It has been reported that SMARCA4 synergizes with RUNX2 to promote EMT in colorectal cancer cells." (PMID 36902184, 2023). "Also, Runx2 was shown to be a key transcription factor that promoted the metastasis of colorectal carcinoma cells." (PMID 28264434, 2017). "High CBX4 expression and low RUNX2 levels are associated with improved survival in colorectal cancer patients, suggesting that enhancing the CBX4-HDAC3 axis could serve as a potential therapeutic strategy for managing metastasis in colorectal cancer." (PMID 40175347, 2025). "Our study of human colorectal cancer tissue microarray (TMA) also revealed positive and statistically significant correlations between the expressions of RUNX1, RUNX2, and RUNX3 in both CD8+T cells and CD103+CD8+T cells." (PMID 39822248, 2024). "In our previous work, we showed a positive correlation between the expression of RUNX2 mRNA in colorectal cancer (CRC) tissue samples and MGP expression; therefore, we wanted to evaluate if RUNX2 affected MGP transcription regulation." (PMID 39684309, 2024). "In colorectal cancer, CBX4 suppresses metastasis by recruiting HDAC3 to deacetylate histone H3K27 at the RUNX2 promoter, consequently inhibiting RUNX2 expression." (PMID 38816356, 2024). "Conversely, in colorectal carcinoma, CBX4 suppresses RUNX2 expression by recruiting HDAC3 to the Runx2 promoter." (PMID 38816356, 2024).
colorectal cancer (continued). "In colorectal cancer, the cell proliferation markers Ki-67 and PCNA were downregulated upon RUNX2 silencing, and RUNX2 was required for CBFβ-elicited cell proliferation." (PMID 37108164, 2023). "In colorectal cancer, CBX4 can interact with histone deacetylase 3 (HDAC3) to maintain recruited HDAC3 to the Runx2 promoter, which maintains a deacetylated histone H3K27 state to inhibit Runx2 expression, consequently repressing tumor metastasis." (PMID 33464142, 2021). "Liquiritigenin, a flavonoid extracted from the roots of Glycyrrhiza uralensis Fisch, inhibited HCT116 colorectal cancer cells invasion and EMT by reduction of Runt-Related Transcription Factor 2 (Runx2) and inactivation of PI3K/AKT signaling." (PMID 32521759, 2020). "Similarly, a study on colorectal cancer (CRC) demonstrated that ITGBL1 was co-expressed with RUNX2 and that RUNX2 regulates the ITGBL1 promoter activity, further supporting the role of RUNX2 in regulating ITGBL1 expression." (PMID 40287769, 2025). "​In colorectal carcinoma, CBX4 suppresses metastasis by recruiting histone deacetylase 3 (HDAC3) to the runt-related transcription factor 2 (Runx2) promoter, leading to transcriptional repression of Runx2, a key factor in cancer metastasis." (PMID 40740235, 2025). "Mechanistically, RUNX2 and CBFβ form a transcriptional complex that binds to promoters and contributes to the upregulation of downstream genes, including OPN, FAM129A, and UPP1, in colorectal cancer HCT116 cells." (PMID 37108164, 2023). "In the present study, we demonstrated that NF-κB but not β-catenin or Runx2, modulated the CCR4-mediated MMP13 activity in colorectal cancer cells, suggesting a crucial function of NF-κB in regulating invasiveness of tumor cells." (PMID 27356745, 2016).
Hyperglycemia (27 papers, 2014 to 2025). An increased concentration of glucose in the blood. "Hyperglycemia and insulin deficiency reduce the expression of runt-related transcription factor-2 (Runx2) and inhibit bone formation." (PMID 32903738, 2020). "In light of these findings, glabridin, which also exhibits estrogenic activity and has also been reported to modulate β-catenin, Runx-2, and osteocalcin expression, could prevent hyperglycemia-induced bone loss through the same mechanism as naringenin and genistein." (PMID 40243576, 2025). "Hyperglycemia and AGEs together suppress proliferation, differentiation and function of osteoblasts, possibly via down-expression of BMPs and Runx2 as well as activation of PPAR-γ signaling." (PMID 36359775, 2022). "Differentiation markers such as Runx2 and osterix exhibit the same behavior in response to high glucose conditions, including hyperglycemia." (PMID 35267965, 2022). "Hyperglycemia suppresses the transcription of Runx2 and SOX9 in periodontal tissues, representing a decreased level of osteoblastic differentiation." (PMID 36359775, 2022). "Mechanistically, our results suggest that PARP-1 regulates hyperglycemia-accelerated arteriosclerotic calcification by targeting Stat1/Runx2 axis." (PMID 31924749, 2020). "The mRNA levels of RUNX2, PPARγ and AdipoQ were also correlated with adipogenesis, which shows chronic hyperglycemia favoring adipogenesis." (PMID 29988028, 2018). "Hyperglycemia also promotes calcification via enhanced alkaline phosphatase expression via the Runx2/Cbfa-1 pathway." (PMID 26185749, 2015). "In addition, through AR activation, hyperglycemia decreases the activity of RUNX family transcription factor 2 (RUNX2), a critical regulator of angiogenesis essential for wound repair." (PMID 41030912, 2025). "In endothelial cells, RUNX2′s DNA binding activity and the angiogenic phenotype were regulated by hyperglycemia, that is, the glucose-mediated intracellular pathway and redox status, suggesting the potential role of RUNX2 in orchestrating tumor-associated angiogenesis." (PMID 37108164, 2023). "Previous studies using animal models of hyperglycemia also reported low expression levels of Runx2." (PMID 35267965, 2022). "The expression of SOX9 and RunX2 were also decreased by hyperglycemia and metformin treatment." (PMID 32841254, 2020). "Once the SIRT1 co-factor NAD+ is diminished via hyperglycaemia it may be unable to competitively inhibit the acetylation of RUNX2, allowing an increase of calcification within the patient." (PMID 30696833, 2019). "Stress (tunicamycin, hyperglycemia)-induced degradation of RUNX2 depends upon active level of AMPK." (PMID 29988028, 2018). "Moreover, hyperglycemia has been shown to inhibit microvascular endothelial cell migration during angiogenesis by suppression of RUNX-2 activity in a wound healing model." (PMID 25742620, 2015). "In the light of our results, Osteocalcin downregulation could result from decreased levels of RUNX-2, which directly regulates Osteocalcin expression as well as from hyperglycemia in db-/db- mice." (PMID 25742620, 2015). "ALP is an early osteoblast marker and Runx2 is a critical transcription factor for osteoblastic differentiation, We found that hyperglycemia interfered with the differentiation of rat osteoblasts, and glimepiride increased the expression of these marker genes at two different glucose concentrations." (PMID 25391146, 2014). "Hyperglycemia and insulin resistance directly decrease osteoblast differentiation and activity by decreasing the expression of osteoblast-related markers, including the Runt-related transcription factor 2 (Runx-2), osteocalcin, bone morphogenetic protein-2 (BMP-2), osteopontin." (PMID 34121973, 2021). "Hyperglycemia also upregulates PPARγ expression of BMMSC, thus inhibiting RUNX2 expression and promoting adipogenesis." (PMID 40873948, 2025).
Hyperglycemia (continued). "GLP‐1RAs promote bone metabolism via Wnt/β‐catenin and Runx2 activation; regulate RANKL/OPG balance; inhibit LPS‐induced osteoclastogenesis; enhance PDLSC osteogenesis under hyperglycemia/inflammation." (PMID 41328144, 2025). "Besides, it has been documented that hyperglycaemia‐induced accumulation of glycation end products could lead to a reduction of blood vessels within the marrow cavity, consequently downregulating osteogenic genes (Runx2 and Oc) in DM mice." (PMID 37621124, 2023). "In an endeavor to understand the negative impact of hyperglycemia and treatment with metformin on alveolar bone repair, the present study evaluated the levels of SOX9, RunX2 and Osterix, transcription factors associated with osteoblast differentiation." (PMID 32841254, 2020). "Most importantly, hyperglycemia exerts a regulatory effect on osteoblasts and osteoclasts; chronic hyperglycemia reduces the ratio of bone biochemical markers, including osteocalcin, AKP, and procollagen type 1 N terminal propeptide, runt-related transcription factor (RUNX2)." (PMID 36188222, 2022). "Hyperglycemia may inhibit genes related to osteogenic transdifferentiation and bone resorption, including metalloproteinase (MMP) 9 and carbonic anhydrase II (CAII), and also decrease the expressions of osteogenesis-related genes such as Runx2 and alkaline phosphatase (ALP)." (PMID 38509497, 2024). "Furthermore, the negative impact of hyperglycemia and/or treatment with metformin also could be noted in the initial stages of bone repair, via inhibition of transcription factors Runx2 and Sox9, involved in osteoblast differentiation." (PMID 32841254, 2020).
lung carcinoma (27 papers, 2012 to 2025). "In lung cancer, RUNX2 had an antiapoptotic effect, and a shRNA-mediated loss-of-function experiment resulted in increased dead cancer cells determined by positive annexin/propidium iodide (PI) in flow cytometry." (PMID 37108164, 2023). "In lung adenocarcinoma, the expression of RUNX2 correlated with a poor hazard ratio, suggesting that RUNX2 plays a clinical role as an independent risk factor for poor survival in lung cancer." (PMID 37108164, 2023). "Upregulation of RUNX2 expression is a feature of many cancer types, including lung cancer, and is associated with proliferation and epithelial-mesenchymal transition." (PMID 36510562, 2022). "RUNX2 is a coregulator of BRCA1, the TF that regulates the LC-PAH CCP, strengthening the evidence that RUNX2 is associated with pulmonary arterial hypertension and lung cancer." (PMID 36551878, 2022). "The WWOX mRNA level is downregulated in tumor tissues by hypermethylation deletion and destabilizing mutations, or it would inhibit RUNX2, reducing the invasiveness of lung cancer cells." (PMID 36551878, 2022). "RUNX2 is also a coregulator of FOXM1, the TF that regulates all LC CCPs, thereby suggesting that RUNX2 is associated with lung cancer development, as it participates in the regulation of important genes coexpressed in several lung cancer networks." (PMID 36551878, 2022). "BMP2-induced lung cancer migration is associated with up-regulation of Runx2 which recruits p300 and in turn enhances histone acetylation, increases Snail expression, and decreases E-cadherin." (PMID 25938545, 2015). "A recent report shows that the migration of lung cancer cells is associated with the upregulation of Runx2 and Snail expression in response to BMP-2 treatment." (PMID 22537242, 2012). "In summary, our results show that the overexpression of RUNX2 in lung cancer is related to its occupancy at different genomic regions, principally at intergenic regions (61%), introns (29%), and promoters-transcription start sites (TSSs) (5%)." (PMID 37754231, 2023). "In this paper, we identified TALAM1 (Metastasis Associated Lung Adenocarcinoma Transcript 1) as a genetic target of the RUNX2 TF in lung cancer and then performed functional validation of the main findings." (PMID 37754231, 2023). "In this work, we demonstrated for the first time that the RUNX2 TF in lung cancer cells functions as a repressor of the expression of the lncRNA TALAM1." (PMID 37754231, 2023). "Specifically, we found that RUNX2 contributes to controlling the expression of lncRNA TALAM1 in lung cancer." (PMID 37754231, 2023). "Despite the multiple roles of RUNX2 in lung cancer initiation and development, the current study is the first attempt to explore the target genes of the transcription factor RUNX2 in lung cancer." (PMID 37754231, 2023). "CoRegNet allowed us to analyze the importance of transcriptional factors as coregulators, leading to an integrated analysis of coexpression and regulatory networks, which highlight RUNX2 as a possibly important transcriptional regulator in NSCLC lung cancer." (PMID 36551878, 2022). "In the present study, we detected increases in RUNX2 expression at the mRNA and protein levels in the A549 lung adenocarcinoma cell line and in tumor tissue of a patient with a diagnosis of lung cancer." (PMID 36510562, 2022). "RUNX2 regulates expression of genes important in tumor cell migration, and has a role in cell proliferation and metastasis of lung cancer." (PMID 36289596, 2022). "The GOLGA8B/miR-30d-5p/RUNX2 regulatory axis has important functions in lung cancer cell proliferation and stemness via regulatory and physical interactions of GOLGA8B and RUNX2 with both stemness-related genes and stemness TFs." (PMID 36289596, 2022). "In lung cancer, RUNX2 directly inhibits ETS1 expression, which is likely to promote angiogenesis, proliferation, invasion, and metastasis." (PMID 36551878, 2022).
lung carcinoma (continued). "For lung cancer, RUNX2 is involved in the epithelial–mesenchymal transition process through the genetic control of vimentin, TWIST, and SNAIL." (PMID 36551878, 2022). "In this study, we found that the increased expression of RUNX2 in the A549 cell line is related to the evasion of apoptosis in lung cancer." (PMID 36510562, 2022). "On the other hand, the CoRegNet library enabled us to analyze the importance of transcriptional regulators in lung cancer, leading to the identification of RUNX2 as an important transcriptional regulator in the process." (PMID 36551878, 2022). "There are other studies that included a network-based approach and integrated driver somatic RUNX2 mutations with LINC01614, a known long non-coding RNA (lncRNA) with a putative regulatory role in lung cancer." (PMID 36551878, 2022). "MicroRNA hsa-mir-196b influences the survival of patients at the second stage of LUAD, which regulates targets Homeobox A9 and Runx2, etc. and acts on early stage lung cancer." (PMID 32428028, 2020). "It was demonstrated that ectopic expression of RUNX2 increases PTHrP expression in neck and lung cancers." (PMID 32204402, 2020). "In lung cancers, RUNX2 overexpression was shown to promote EMT via direct regulation of vimentin along with other proteins." (PMID 32204402, 2020). "In this study we identified a mechanism by which Runx2 transcription factor contribute to epigenetic silencing of a tumor growth inhibitor BMP-3B in lung cancer cells." (PMID 22537242, 2012). "In summary, our study demonstrates BMP-3B as a novel target gene for Runx2 in bone lineage and lung cancer cells and provides insight into mechanisms that regulate epigenetic silencing of tumor growth inhibitors in lung cancer cells." (PMID 22537242, 2012). "Our studies identified BMP-3B as a new Runx2 target gene and revealed a novel function of Runx2 in silencing of BMP-3B in lung cancers." (PMID 22537242, 2012). "The Western blot analysis for Runx2 protein levels further validated increased Runx2 levels in lung cancer cells compared to normal lung fibroblast cells." (PMID 22537242, 2012). "To examine the phenotypic effects of Runx2 overexpression in lung cancer cells, we assessed proliferation and migration potential of H1299-Runx2 cells or H1299- empty vector cells." (PMID 22537242, 2012). "To further investigate the mechanism of Runx2-mediated downregulation of the BMP-3B expression in lung cancer cells, we performed chromatin immunoprecipitation analysis in H1299 cells expressing either wild type Runx2 or shRunx2." (PMID 22537242, 2012). "Our results showed that Runx2 expression is increased in metastatic lung cancer cells (H1299) compared to normal lung fibroblast cells." (PMID 22537242, 2012). "Our studies with Runx2 overexpression or knockdown in lung cancer cells indicate that Runx2-mediated downregulation of BMP-3B is via increasing histone H3K9 methylation status of the proximal promoter by interacting with methyltransrefase Suv39h1." (PMID 22537242, 2012). "Our results suggest that Runx2 is a potential therapeutic target to block tumor suppressor gene silencing in lung cancer cells." (PMID 22537242, 2012). "Our studies with modulation of Runx2 levels in lung cancer cells indicate that Runx2-mediated downregulation of BMP-3B levels is via interacting with methyltransrefase Suv39h1 and increasing histone H3K9 methylation status of the proximal promoter." (PMID 22537242, 2012). "Further studies are required to definitely establish the contribution of Runx2 in lung cancer progression." (PMID 22537242, 2012). "In previous reports, we identified the RUNX2 TF as a possible biomarker for lung cancer." (PMID 37754231, 2023).